NTRK1 (neurotrophic receptor tyrosine kinase 1)
Diseases named in the same sentence as NTRK1 in open-access papers (continued):
Sharing a sentence is not in itself a finding about the gene and the disease.
cancer (continued). "The predominant follicular pattern was more common in NTRK3 than in NTRK1 fusion-positive carcinomas, in which the follicular architecture mostly co-occurred with foci of papillary formation." (PMID 33923728, 2021). "NTRK1-rearranged carcinomas showed a higher frequency of multifocality and aggressivity than NTRK3-rearranged carcinomas." (PMID 33923728, 2021). "The patients with carcinomas harboring NTRK1 fusions had LN metastases 80% of the time compared to 49% of time for NTRK3 fusion-positive carcinomas." (PMID 33923728, 2021). "At present, systematic analyses of large cohorts of metastatic cancer patients for the presence of NTRK1/2/3 fusion genes across cancer types are yet to be carried out." (PMID 32466202, 2020). "Remarkable success has been achieved by targeting oncogenic gene fusions including diverse tyrosine kinase inhibitors against fusions involving ALK, ROS1, RET, FGFR1/2/3, and NTRK1/2/3 in non-small-cell lung cancer and across a wide spectrum of cancer types." (PMID 32411236, 2020). "Luminal A and luminal B cancers presented with NTRK1 alteration in 7% and 8% of cases, respectively." (PMID 32957504, 2020). "Fusions with ADK, BRAF, and NTRK1 were reported repeatedly both in our cohort and in multiple cancer types." (PMID 32471990, 2020). "NTRK (NTRK-1, 2, 3) translocations have been observed in <1% of cancers and in more than 20 cancer types." (PMID 31032221, 2019). "We identify BRAF and NTRK1 as additional cancer genes operative in both malignancies, substantiating the view that these diagnoses represent variants on the same disease spectrum converging on aberrant RAS-RAF-MEK-ERK signaling." (PMID 29915264, 2018). "The NTRK1 IHC was significantly (p < 10−4) higher in the cancer cell nests of HNSCC than in the normal epithelium of the UPPP samples." (PMID 29904026, 2018). "Considerable research has been conducted in targeting the NTRK1-NGF axis in drug development for pain management and for targeting NTRK1, 2, 3 as oncogenes in 19 different types of cancer." (PMID 29568395, 2018). "In contrast, in HNSCC apparently all cells in the cancer cell nests were stained with NTRK1 antibody." (PMID 29904026, 2018). "Over 80% of HNSCC specimens showed positive reaction for high affinity NGF receptor, NTRK1, and nearly all of them a high positive reaction in cancer cell nests." (PMID 29904026, 2018). "In a sample of 14 HNSCC specimens containing both NTRK1 and p75NTR staining in the cancer cell nests, the staining intensity was evaluated by HistoQuest." (PMID 29904026, 2018). "Further studies containing larger cohorts are necessary to clarify the clinical characteristics of NTRK1‐fusion‐positive cancers." (PMID 29125233, 2017). "Inhibition of the TrkA kinase is a promising targeted therapy for cancer patients whose tumors harbor a NTRK1 rearrangement." (PMID 26472021, 2015). "We also detected several low-frequency, pan-cancer kinase fusion events, for example in the neurotrophic tyrosine receptor kinases NTRK1, NTRK2 and NTRK3, that drive tumorigenesis in a small fraction of multiple cancers, regardless of tissue type." (PMID 25204415, 2014). "The relationship between NTRK1/2/3 expression and cancer signalling pathways is fairly established." (PMID 41155675, 2025). "discussed resistance mechanisms in NTRK1‐rearranged cancers including TPM3‐NTRK1." (PMID 41275415, 2025). "Moreover, there was enrichment of known cancer signalling pathways in the NTRK1/2/3-high subsets of CRC." (PMID 41155675, 2025). "Of the kinase inhibitor gene targets evaluated, high pre-treatment PIKFYVE, KDR, NTRK1, IKBKB, FLT1, or FGFR1 expression was each associated with lower odds of achieving CR when controlling for cancer type, biopsy site, age at the time of treatment initiation, and ICB agent." (PMID 38464258, 2024). "Indeed, in several cancers, cells with NTRK1 fusions have been shown to be responsive to tyrosine kinase inhibitors (TKIs) in vitro and in vivo." (PMID 37046604, 2023).
cancer (continued). "Interestingly, unlike Lestaurtinib, Larotrectinib and Entrectinib have been approved only for cancers with an oncogenic NTRK1 fusion." (PMID 37046604, 2023). "A central goal of this study was to generate novel murine Ret and Ntrk1 cancer models." (PMID 37470475, 2023). "The increased signaling by the “NTRK1 (neurotrophic tyrosine receptor kinase gene fusion)” term could promote cancer cell growth." (PMID 37834191, 2023). "In recent years, special attention has been paid to NTRK1 fusions in cancers." (PMID 37046604, 2023). "Thus, it has been directly demonstrated that overexpression of the MAP-kinase pathway in cancers harboring an NTRK1 fusion is responsible for resistance to Larotrectinib and LOXO-195." (PMID 37046604, 2023). "However, NTRK1–3 rearrangements compose the majority of the gene translocations observed in MSI-positive carcinomas." (PMID 37686416, 2023). "The family of NTRK genes consists of NTRK1-3 encoding TRKA, TRKB and TRKC proteins that play a role in development and functioning of the nervous system, and act as drivers of oncogenesis in various cancers." (PMID 35237889, 2022). "Many drugs have been developed for the treatment of NTRK1-rearanged cancers." (PMID 36531058, 2022). "In particular, c-MET and NTRK1 were identified as regulators of matrix alignment and may serve as novel targets within the cancer stroma." (PMID 36530465, 2022). "FusionPlex CTL and/or TruSight RNA Pan-Cancer NGS panels confirmed the seven NTRK1 fusions." (PMID 35237889, 2022). "To check whether an IR-induced G2 checkpoint defect is specific for TrkA/NTRK1 or is a general consequence of tyrosine kinase activation in cancer cells, we used EGFR-overexpressing lung cancer cells, A549 and H1975, as a control." (PMID 34885133, 2021). "A total of 17% (14 cases) of basal (triple-negative) cancers had alterations within the NTRK1 gene." (PMID 32957504, 2020). "The discovery of driver oncogenes with aberrant tyrosine kinase activation, such as ALK, ROS1, RET, or NTRK1 gene rearrangement in cancers, continues to change the therapeutic strategies and treatment regimens accompanied with the development of targeted therapies." (PMID 32871626, 2020). "The identification of fusion driver oncogenes with aberrant tyrosine kinase activation, such as ALK, ROS1, RET, or NTRK1 rearrangement in cancers, is largely changing therapeutic strategies accompanied with the development of targeted therapies, especially potent TKIs." (PMID 31399568, 2019). "We also analyzed whether another member of the same family, Ntrk3, can impact KP cancer cell biology in a similar manner as Ntrk1." (PMID 30986992, 2019). "Few reports exist on the incidence of brain metastasis in NTRK1‐fusion‐positive cancers." (PMID 29125233, 2017). "Therefore Inhibition of the TrkA kinase is a promising targeted therapy for cancer patients whose tumors harbor a NTRK1 rearrangement." (PMID 26472021, 2015). "This established evidence in various cancer types suggests that oncogenic rearrangement of NTRK1 might occur at low frequency across many other cancer types." (PMID 26472021, 2015). "The involvement of NTRK1 in GBM has been largely unknown, but NTRK1 is involved in other types of cancer." (PMID 24647444, 2014). "The GSEA and DOEA showed that NTRK signalling was enriched for kinase inhibitors responses, representing evidence that NTRK1/2/3 expression may serve as biomarkers for multiple kinase inhibitors, including entrectinib—the tissue-agnostic kinase inhibitor for cancers with NTRK gene fusions." (PMID 41155675, 2025).
cancer (continued). "Fusions of NTRK1, NTRK2, and NTRK3 and their partner genes can lead to overexpression of Trk proteins, which in turn activate downstream signaling pathways, such as RAS/MAPK, PI3K/AKT, and PLC-γ, causing transformation, proliferation, and survival of cancer cells." (PMID 41383499, 2025). "Similarly, an NTRK1-driven transcriptional profile related to neuronal and neuroectodermal lineage was upregulated mainly in hES-MP, supporting the importance of appropriate cellular context in modeling cancer relevant aberrations." (PMID 36801905, 2023). "Tropomyosin receptor tyrosine kinase A (TrkA) is a neurotrophic receptor encoded by the NTRK1 gene and is implicated in numerous cancer types, in part, due to its propensity for forming oncogenic NTRK fusion genes that drive the malignant progression of some cancer types." (PMID 34066153, 2021). "Accordingly, compound 1g was found to inhibit TRKA (neurotrophic tyrosine receptor kinase 1, NTRK1), DYRK1A/1B (dual specificity tyrosine-phosphorylation-regulated kinase 1A and 1B), and CK1δ (casein kinase 1 delta, CSNK1D) kinases, reportedly associated with overexpression in cancer cells." (PMID 34959689, 2021). "A total of 1,501 distinct fusions in at least one of the nine driver genes assessed (ALK, RET, ROS1, NTRK1/2/3, FGFR2, FGFR3, and NRG1) were detected in 1,497 patients for a combined prevalence of 2.2% across the pan-cancer cohort." (PMID 41091579, 2025). "The findings demonstrated that the main mechanisms of NTRK1/2/3 expression deregulation in CRC are the established and most common mechanisms of gene deregulation in cancers." (PMID 41155675, 2025). "Of the fusion genes that have matched FDA-approved targeted therapy in at least one cancer, only RET and NTRK1/2/3 have FDA approvals that are tumor type–agnostic." (PMID 41091579, 2025). "Basket trials have shown the efficacy of therapies targeting fusion drivers across solid tumors, leading to pan-cancer approvals for RET and NTRK1/2/3 fusions." (PMID 41091579, 2025). "Previous studies have highlighted the mutual involvement of NTRK1 and IGF2 in development and cancer." (PMID 40722704, 2025). "Gene fusions such as TPM3—NTRK1, TPM3—ALK, and TPM3—ROS1 have been identified as oncogenic drivers in various cancers." (PMID 41275415, 2025). "Rearrangements involving the neurotrophic-tropomyosin receptor kinase (NTRK) gene family (NTRK1, NTRK2, and NTRK3) have been identified as drivers in a wide variety of human cancers." (PMID 38863624, 2024). "These fusion proteins are formed when the NTRK family genes NTRK1, NTRK2, and NTRK3 fuse with other genes, leading to abnormal activation of signalling pathways that promote cancer cell growth and survival." (PMID 39014476, 2024). "We analyzed 8,805 3’ kinase gene fusions curated from the COSMIC, focusing on the seven most common kinase fusions involving ALK, RET, ROS1, NTRK1, NTRK3, ABL1, and BRAF genes found in various types of cancers." (PMID 38877018, 2024). "NAB2–STAT6 fusions have been shown to function as transcriptional activators and upregulate the expression of cancer-promoting EGR1 target genes including FGFR1 and NTRK1, as well as IGF genes in SFT patient samples." (PMID 37370737, 2023). "These tyrosine kinase receptors have received some attention from the clinical point of view, given that NTRK gene fusions including NTRK1, NTRK2, and NTRK3 are identified as oncogenic drivers in various types of tumors, including an increase in cancer in DM1." (PMID 36767649, 2023). "Important endocrine system and cancer-related genes and pathways appear to be dysregulated among WTC-exposed individuals; these include WRN, BRCA1, NOTCH1, and NTRK1, among others." (PMID 38131903, 2023). "Among the 49 VUS identified in the index patient 1, two genes were cancer-related: NTRK1c.16C > T and NFATC2 c.1952G > A. Gene fusions involving NTRK1 can confer oncogenic potential in several tumors, including BC and CRC." (PMID 37628631, 2023).
cancer (continued). "Gene fusions involving NTRK1, NTRK2, and NTRK3 are rare drivers of cancer that can be targeted with histology-agnostic inhibitors." (PMID 35328221, 2022). "Among the three NTRK genes, NTRK1 and NTRK3 gene fusions can be identified in a wide range of cancer types, NTRK3 fusion is the most common followed by NTRK1 fusion, and ETV6-NTRK3 along with TPM3-NTRK1 are the most common fusion partners." (PMID 35372074, 2022). "There is increasing evidence that nerve growth factor (NGF) and its receptors, the neurotrophic receptor tyrosine kinase 1 (NTRK1/TrkA), the common neurotrophin receptor (NGFR/p75NTR) and the membrane receptor sortilin, participate in cancer growth." (PMID 35457078, 2022). "Nevertheless, NTRK1 expression was shown to significantly correlate with immune cell infiltration levels, such as the CD8+ T cells currently used in cancer immunotherapy." (PMID 35627227, 2022). "Subsequent studies have shown that in this type of carcinoma, NTRK rearrangements take place in the tyrosine kinase domain of the NTRK1 gene and the 5 ′end of the 3 partners (TRKT1, TRKT2 and TRKT3)." (PMID 35860155, 2022). "These types of childhood cancers share common features including the aberrant expression of receptor tyrosine kinases (RTK) such as KIT and NTRK1." (PMID 34944663, 2021). "Among the FASTKs interactors involved in cancer development, the best understood ones are EGFR, NTRK1 and FBXO6." (PMID 34768773, 2021). "Neurotrophic Receptor Tyrosine Kinase 1 (NTRK1) inhibition suppressed YAP-driven transcription, cancer cell proliferation, and migration." (PMID 33431791, 2021). "Chromosomal translocations involving the NTRK1, NTRK2, and NTRK3 genes result in constitutive activation and aberrant expression of TRK kinases in numerous cancer types." (PMID 32466202, 2020). "The gene fusion occurs when the NTRK 1/2/3 genes fuse with other genes, resulting in altered TRK protein (TRKA, TRKB, and TRKC) that activate signaling pathways for the proliferation of certain types of cancer." (PMID 32380712, 2020). "Before investigating the protein level of TrkA using immunohistochemistry, we performed data mining of TrkA (NTRK1) gene expression, using the cBioPortal cancer genomics platform of the PAM50 dataset from The Cancer Genome Atlas (TCGA) database." (PMID 32957504, 2020). "BMS-777607 is currently undergoing phase II clinical trials for a number of different cancers, including breast cancer, and has activity against MET (IC50 3.9 nM), MERTK (IC50 14 nM) and NTRK1 (IC50 290 nM)." (PMID 30898150, 2019). "Oncogenic fusion genes involving the NTRK family (NTRK1, NTRK2, or NTRK3) have been identified in various cancers, and a few NTRK-TKIs have been effective against the NTRK-rearrangement-positive cancers in clinical trials." (PMID 31399568, 2019). "MGCD516 (Mirati Therapeutics Inc., San Diego, CA, USA) is another multi-kinase inhibitor in a phase 1/1b clinical trial (NCT02219711) for patients with advanced cancers expressing rearranged MET, RET, AXL, NTRK1, or NTRK3 genes." (PMID 29617282, 2018). "Kinase fusion genes detected across multiple cancer types include RET, NTRK1, NTRK3, ALK, ROS1, FGFR1/2/3, and serine threonine kinases including the RAF family genes BRAF, RAF1, CRAF, and MAST1/2." (PMID 26684754, 2015). "Second, our pipeline was able to recapitulate most known translocation events in cancer (ALK, BRAF, EGFR, FGFR1, 2 and 3, NTRK1, 2 and 3, PDGFRA, PRKCA, RAF1, RET, ROS1)." (PMID 25204415, 2014). "NTRK1 is a mediator of the pro-survival signaling of nerve growth factor (NGF) and is a known oncogene, found commonly altered in human cancer." (PMID 24647444, 2014). "The findings of this study, specifically, the enrichment of PI3K-Akt, EGFR, MAPK, AMPK and ERK signalling in the NTRK1/2/3-high CRC subsets, are in consonance with the established signalling relationships of NTRK1/2/3 expression with cancer signalling pathways." (PMID 41155675, 2025).
cancer (continued). "Furthermore, GSEA and POEA demonstrated that NTRK1/2/3-high CRC subsets exhibited enrichment of and cross-talks among the NTRK signalling pathways, as well as of known cancer signalling pathways." (PMID 41155675, 2025). "Fusion-negative NTRK1/2/3 expression demonstrated correlations with clinicopathological and molecular features of CRC, as well as associations with cancer-relevant signalling pathways." (PMID 41155675, 2025). "Additionally, HRi tumors demonstrated DEGs of kinase pathways including PI3K/AKT signaling in cancer (FE = 11.5, FDR = 8.88 × 10−3), ALK (FE = 22.7, P = 0.0276), and NTRK1 (FE = 8.1, P = 0.0330)." (PMID 40796942, 2025). "Moreover, numerous oncogenic drivers (ALK, BRAF, EGFR, MET, NRG1, NTRK1/2/3, RET, and ROS1) involved in sole reciprocal fusions were found in those cancers." (PMID 39254060, 2024). "Through the NGF-Neurotrophic Receptor Tyrosine Kinase 1 (TrkA)-Nerve Growth Factor Receptor (NGFR) axis, Schwann cells exhibit robust chemotaxis towards neoplastic cells, in which participate in neural regeneration around cancer cells." (PMID 37524695, 2023). "Overall, CYP1B1, NTRK1, and NFATC2 are not related to cancer risk but have potential roles as prognostic markers and actionable drug targets." (PMID 37628631, 2023). "The ITPR1 variant could be altering the inflammatory and immune response involved in the pathogenesis of conditions such as cancer since this function is enriched in the MetaScape analysis by this and other candidate genes (FOXM1, CACNA2D1 and NTRK1)." (PMID 37175550, 2023). "Overall, DeepAlloDriver highlights the strong correlation between protein structure and function as well as the superior ability of EGNNs to predict allosteric driver mutations, and the effectiveness of the server was validated in the cancer drivers RRAS2 and NTRK1." (PMID 37078611, 2023). "In addition to ALK, RET, NTRK1, and ROS1, fusions involving FGFR1/2/3 and NRG1 genes have been reported in NSCLC among other cancers and represent emerging therapeutic targets." (PMID 35328282, 2022). "By comparing focal SCNAs in matched NSCLC-BM pairs, we identified putative BM-driving alterations affecting multiple cancer genes, including several potentially targetable alterations in genes such as CDK12, DDR2, ERBB2, and NTRK1, which we validated in an independent cohort of 84 BM samples." (PMID 36561283, 2022). "In addition, gilteritinib was effective against NTRK-rearranged cancers including entrectinib-resistant NTRK1 G667C-mutant and ROS1 fusion-positive cancer." (PMID 33627640, 2021). "Moreover, gilteritinib effectively inhibited the NTRK1 fusion protein and suppressed the growth of NTRK-rearranged cancer." (PMID 33627640, 2021). "The involvement of NTRK1 in GBM remains unknown, however, it is frequently involved in other cancers." (PMID 34671307, 2021). "However, in cancer, NTRK is often observed as a fusion oncogene, such as TPM3-NTRK1, which induces constitutive activation of NTRK1 tyrosine kinase resulting in cancer progression." (PMID 31399568, 2019). "This is particularly interesting because NTRK1 is a membrane-bound receptor that phosphorylates itself and members of the MAPK pathway and it is already known that it confers resistance to cancer chemotherapy by activating p38 mitogen-activated protein kinase signaling pathways, where RIT1 belongs." (PMID 31105872, 2019). "p75NTR protein synthesis was not more frequent in cancer cell nests than in normal mucosa, but NTRK1 staining was significantly higher in the cancer cell nests of HNSCC than in the normal epithelium." (PMID 29904026, 2018). "In few cases, 7 of 93 HNSCC, the opposite was found: a broad p75NTR staining in epithelial cancer cell nests (green reaction), without NTRK1 staining." (PMID 29904026, 2018).